SEC62 (SEC62 preprotein translocation factor)
Diseases named in the same sentence as SEC62 in open-access papers (continued):
Sharing a sentence is not in itself a finding about the gene and the disease.
cancer (continued). "Besides, evidence accumulated that Sec62 substantially contributes to cancer cell malignancy by activating diverse signalling pathways." (PMID 36200182, 2022). "These combined studies suggest that the recov-ER-phagy mediated by SEC62 may help cancer cells to better cope with ER-stress, and promote their survival and migration." (PMID 34571977, 2021). "Lastly, expression levels of Sec62 and Sec63 are found to be altered in various cancer cells." (PMID 34884562, 2021). "Elevated expression of Sec62 has been observed in some cancer tissues." (PMID 34884562, 2021). "Recent studies have uncovered that Sec62 is upregulated in various human cancers." (PMID 33858476, 2021). "However, from a functional point of view only few studies addressed the specific impact of altered SEC62 expression levels on cancer cell biology." (PMID 33925740, 2021). "For example, if SEC62 amplification in cancer does permit aberrant cancer cell survival, inhibition of this pathway could be envisaged as a therapeutic option." (PMID 31100386, 2020). "SEC62 amplification may be consistent with a double-edged sword role for the UPR in cancer progression; the UPR can drive cancer progression but paradoxically also engages cancer cell death." (PMID 31100386, 2020). "Additionally, we observed looping interactions to a number of genes at 3q26.2 including SEC62, which has been proposed as a cancer biomarker." (PMID 30602759, 2018). "3q26 amplification represents a highly frequent chromosomal alteration in HNSCCs and encodes the genes SEC62 and SOX2, which have both been shown to be overexpressed in various cancers, including HNSCCs, and to affect the metastatic potential of cancer cells." (PMID 28002801, 2017). "SEC62 over-expression was found to result in elevated migratory potential and increased stress tolerance of the respective tumor cells, i.e., two “hallmarks” of cancer cells with a connection to cellular Ca2+ homeostasis." (PMID 29163222, 2017). "In addition, the SEC62 protein level of the cancer tissue significantly correlated with a positive lymph node status and indicated poorer overall survival." (PMID 28002801, 2017). "Moreover, a high expression of SEC62 predicts a poorer clinical outcome for this cancer entity and crucially influences cell migration, calcium homeostasis and ER stress tolerance of various human tumor cells." (PMID 27553742, 2016). "We also found that the treatment of different human cancer cells with calmodulin antagonists led to the same cellular phenotypes as observed after SEC62 silencing, namely cell migration inhibition and markedly higher cell sensitivity to thapsigargin-induced ER stress." (PMID 24304694, 2013). "This approach provided new insight into the physiological function of Sec62 and may lead to a new therapeutic strategy for personalized cancer therapy." (PMID 24304694, 2013). "In future studies, different cell culture experiments, with a focus on cell proliferation, cell migration, and cell invasion, may shed light on the detailed influence of Sec62 on relevant molecular processes of carcinogenesis, as well as the wider hallmarks of cancer cell biology." (PMID 33915997, 2021). "Therefore, it can be speculated that C53, like SEC62, may help cancer cells cope with ER stress and promote their survival through upregulating ER-phagy." (PMID 34571977, 2021). "Together, these data strongly indicate a role of SEC62 as a driver oncogene in various human cancers with a consistent association with poor prognosis, lymph node as well as distant metastasis and stress tolerance, which turns the Sec62 protein into an attractive target for anticancer therapy." (PMID 33925740, 2021). "Using calmodulin antagonists, including TFP, we can inhibit cancer cell migration and overcome the problem of Sec62 overproduction in response to thapsigargin, which may also improve the treatment of these cancer entities in future combinatorial therapeutic strategies." (PMID 24304694, 2013).
cancer (continued). "These were functionally characterized especially for the relevance of SEC62 in HNSCC and its role in cancer cell proliferation and migration." (PMID 36045752, 2022). "We further show that depletion of Sec62 sensitizes CRC cells to drug treatment and attenuates cancer stemness." (PMID 33858476, 2021). "Accordingly, depletion of Sec62 decreased the expression of Wnt target genes including AXIN2, LGR5 and MYC, all of which play critical roles in maintaining cancer cell stemness and CRC progression." (PMID 33858476, 2021). "Overall survival across all cancer entities recorded in the TCGA atlas was shorter in patients with SEC62 alteration compared to patients without SEC62 alteration (p < 0.01)." (PMID 36685175, 2022). "Sec62 was upregulated in the cancer tissues compared with non-cancerous tissues and significantly increased at clinical stage IV." (PMID 33858476, 2021). "However, the broad influence of a potentially dysregulated ER-phagy in SEC62 overexpressing cancer cells cannot be ruled out." (PMID 33925740, 2021).
tumor (23 papers, 2010 to 2023). "In hepatocellular carcinoma, high SEC62 expression correlated with a higher risk of tumor recurrence." (PMID 38201525, 2023). "A first step to uncover potential associations of SEC62 overexpression with tumor cell biology are correlation analyses with clinical data." (PMID 33925740, 2021). "SEC62 alterations, classified as mutations, amplifications, deep deletions, and multiple alterations, were detected in 10,967 (12.61%) of 86,962 analyzed cases of 32 tumor entities in the TCGA database." (PMID 37298528, 2023). "Indeed, a following systematic interrogation of 3q26 by gain- and loss-of-function studies identified SEC62/TLOC1 as a ‘tumor-driver gene’ encoded in this region." (PMID 29263911, 2017). "Therefore, it appears that Sec62 may be a diagnostic and prognostic marker as well as a therapeutic target for various tumors, which warranted murine tumor models as the next logical step." (PMID 36262254, 2022). "Therefore, we could reasonably assume that abnormality in metastasis‐associated precursor protein depending on Sec62 trafficking may occur during tumour metastasis." (PMID 36200182, 2022). "Its role in tumor cell biology and potential therapeutic strategies targeting SEC62 should be further investigated." (PMID 38201525, 2023). "Here, higher SEC62 expression levels were observed in lymph node metastases compared with the primary tumor in HNSCC patients, as well as in lymph node metastases from CUP patients compared to lymph node metastases from HNSCC patients." (PMID 38201525, 2023). "Correlation analysis revealed that Sec62 positively related with the larger tumour size, the more lymph node metastasis, and the higher AJCC stage." (PMID 36200182, 2022). "The human SEC62 gene is located on chromosome 3q, was characterized as a tumor driver gene and is found to be overexpressed in an ever-growing number of tumors, particularly those with 3q26 amplification." (PMID 36262254, 2022). "This process of recovER-phagy is highly characteristic for tumor cells expressing high amounts of SEC62 and therefore distinguishes tumor cells from surrounding cells and makes tumor cells potentially accessible for SEC62 targeted treatment." (PMID 36045752, 2022). "Depletion of Sec62 from either type of SEC62 overexpressing tumor cells by treatment with SEC62-targeting siRNAs leads to reduced stress tolerance and reduced migratory as well as invasive potential." (PMID 36262254, 2022). "SEC62 expression in tumor tissue samples taken during clinical treatment was assessed immunohistochemically, with the calculation of immunoreactivity scores according to Remmele and Stegner, Pathologe, 1987, 8, 138–140." (PMID 36685175, 2022). "Where tested, treatment of SEC62 overexpressing tumor cells with the small molecule/calmodulin antagonist trifluoperazine (TFP) phenocopied the effect of SEC62-targeting siRNAs." (PMID 36262254, 2022). "Against the background of stimulation of tumor metastasis and the increased tolerance to ER stress and worsened prognosis in SEC62 overexpression, Sec62 presents itself as a potential target structure of a targeted antitumor therapy." (PMID 36262254, 2022). "Next, paired CRC and non‐tumour clinical samples were used to evaluate the level of Sec62 by qRT‐PCR and western blot." (PMID 36200182, 2022). "The nude mice bearing tumor xenograft were injected with control lentivirus (shCtrl) or Sec62 shRNA (shSec62)-lentivirus." (PMID 33858476, 2021). "High frequency of mutation and overexpression of SEC62 and SEC63 have been observed in kinds of cancers, suggesting the potential role of ER protein in tumor development." (PMID 34774014, 2021). "Regarding the functional role of Sec62 in tumor cell biology, it was shown that high Sec62 levels are able to stimulate the migration and invasion of tumor cells." (PMID 33915997, 2021). "The results showed that Sec62 knockdown effectively attenuated tumor growth as 5-Fu or oxaliplatin did." (PMID 33858476, 2021).
tumor (continued). "Mutations that occurred in SEC62 and FAM134B genes are involved in cancer progression and development, i.e., FAM134B mutations in esophageal squamous cell carcinoma promotes tumor development while in colon cancer, it leads to tumor suppression." (PMID 34071600, 2021). "In this study, we evaluated the immunohistochemical expression of Sec62 in tumour tissues from a prospective cohort of 60 HCC patients." (PMID 31822656, 2019). "Meanwhile, Western blot analysis showed that the Sec62 levels in tumour tissues with early recurrence were much higher than those from non-recurrent tumours." (PMID 31822656, 2019). "Accumulating evidence showing that Sec62 is highly elevated in the tumor microenvironment point toward a HIF-1-dependent regulation of Sec62 upon hypoxia induction." (PMID 30250843, 2018). "We reasoned that if Ca2+-calmodulin secures efficient Sec61 channel closure in cooperation with Ca2+-Sec62, calmodulin antagonists should mimick the effect of SEC62 silencing on SEC62 over-expressing tumor cells; indeed, this is what we found." (PMID 29163222, 2017). "The clinical relevance of the Sec62 protein level for SCC of the lung is even more important given that the increased Sec62 protein level also protects tumor cells from thapsigargin therapy." (PMID 24304694, 2013). "Previously, we showed that Sec62 depletion inhibits the spread of metastatic tumor cells and increases cell sensitivity to Ca2+-driven ER stress." (PMID 24304694, 2013). "Sec62 is essential for cell migration and protects tumor cells against thapsigargin-induced ER stress, which are both linked to cytosolic Ca2+." (PMID 24304694, 2013). "Overproduction of Sec62 is also observed in other tumors, primarily in tumors of the lung and thyroid." (PMID 22682366, 2012). "SEC62 expression stimulated tumor cell migration (p ≤ 0.01)." (PMID 37298528, 2023). "In the next step, we correlated SEC62 expression levels on tumor cells with the patients’ clinical and histopathological data, including tumor size, nodal status, distant metastasis, tumor differentiation, tumor localization, p16 status, nicotine consumption, patient age, and gender." (PMID 38201525, 2023). "In this study, we firstly discovered that ER‐resident Sec62 was generally upregulated in CRC using CRC cell lines, clinical samples and public databases, which was positively associated with tumour size, AJCC stage, lymph node metastasis rate and patients' poor prognosis." (PMID 36200182, 2022). "Consistently, Sec62 was highly expressed in CRC compared with non‐tumour tissues." (PMID 36200182, 2022). "While this phenotype could be rescued by SEC62 overexpression, a SEC62 knock-down sensitized tumor cells to TG- and/or TFP-induced ER-stress proving this concept of anti-metastatic and potentially anti-proliferative therapy." (PMID 36045752, 2022). "Also, measurements of Ca2+ concentrations under physiological conditions in SEC62-knockout cells should be performed to further characterize a stable depletion of SEC62 and its consequences for the molecular environment of a tumor cell." (PMID 36045752, 2022). "From the molecular background, there are three hypotheses why tumor cells with elevated SEC62 levels show a higher resistance to ER-stress conditions." (PMID 36045752, 2022). "However, the exact molecular mechanisms of how Sec62 can influence tumor cell migration and invasion through a regulation of cytosolic calcium levels remain elusive." (PMID 33915997, 2021). "Additionally, high Sec62 levels help tumor cells to compensate ER stress induced by an overload of unfolded or misfolded proteins in the ER lumen using a Sec62 mediated mechanism called recovER-phagy." (PMID 33915997, 2021). "Additionally, high Sec62 levels correlated significantly with higher tumor size (T stage), the presence of tumor ulceration, and the presence of lymph node as well as distant metastases." (PMID 33915997, 2021).
tumor (continued). "In addition, the observation that low Sec62 levels sensitize tumor cells to TG-induced ER stress is of potential clinical relevance." (PMID 29263911, 2017). "Based on our data on the role of Sec62 in Sec61 channel gating, we asked whether the effect of SEC62 silencing on SEC62 over-expressing tumor cells can be phenocopied by drugs." (PMID 29163222, 2017). "Furthermore, it provides the first molecular insight into the mechanism of resistance of Sec62-overproducing tumor cells to treatment with thapsigargin." (PMID 24304694, 2013). "Therefore, Sec62 is not only a predictive marker for this type of tumor, but also an interesting therapeutic target." (PMID 24304694, 2013). "Despite the important roles of cyclin B1 and Sec62 in tumor recurrence and their predictive implications, this study should be viewed as a hypothesis-generating study." (PMID 22682366, 2012). "It is speculated that FAM134B, CCPG1, and TEX264 are receptors for common ER-phagy in tumor development, while SEC62 may be more significant in the recovery process after anticancer compound treatment, and RTN3L may have a hand in the degradation of the tubular ER." (PMID 35327508, 2022). "First, because of its role in protein translocation elevated SEC62 levels could help tumor cells to recover from defects in the regulation of this process i.e. the accumulation of misfolded proteins in the ER by facilitating a more efficient intracellular protein transport." (PMID 36045752, 2022). "Also in 2013, the SEC62/TLOC1 gene was characterized as tumor driver gene." (PMID 36262254, 2022). "This clued that Sec62 may regulate tumour metastasis via influencing calcium homeostasis in ER." (PMID 36200182, 2022). "Thus, targeting Sec62 in patients who have undergone HCC resection might improve their surgical outcome via effective inhibition of tumour relapse and metastasis." (PMID 31822656, 2019). "Furthermore, the SEC62 gene has been characterized as a “tumor driver gene”." (PMID 29163222, 2017). "Additional studies are needed to determine whether the role of Sec62 as a prognostic marker is solely because of the tumor cells’ dependency on a sufficient Sec62 level to enable metastasis and resistance to Ca2+-driven cellular stress, or whether Sec62 has additional contributing functions." (PMID 24304694, 2013). "In this study, we further evaluated the function of SEC62 in TNBC, focusing on its role in predicting the response to NACT and its function in tumor cell biology." (PMID 37298528, 2023). "Correlations of SEC62 expression with the TNM stage, histological subtype, tumor entity, and oncological outcomes (progression-free and overall survival) were examined." (PMID 36685175, 2022). "In search of alternative mechanisms to inhibit Sec62 function, it was shown that treating tumor cells with the CaM antagonist TFP both in terms of migratory potential and cellular calcium homeostasis achieves the same phenotype as SEC62 silencing." (PMID 36262254, 2022). "On the contrary, SEC62 overexpression stimulated migration of HEK293, HeLa, Huh-7 and FaDu cells and induced subcutaneous tumor growth in C.Cg/AnNTac-Foxn1nu/nu mice, inoculated with SEC62 overexpressing HMLE cells." (PMID 33925740, 2021). "Over the past 15 years, increasing evidence suggests a relevant role of SEC61, SEC62, and SEC63 genes in the development and tumor cell biology of human malignancies." (PMID 33925740, 2021). "To further investigate the function of Sec62 in early HCC recurrence, we generated mice bearing orthotopically implanted tumours formed from luciferase-labelled Lv-Sec62KD, Lv-Sec62OE, or Lv-NC Huh7 cells." (PMID 31822656, 2019). "When comparing the expression levels of SEC62 and SOX2 in the primary tumor tissue of HNSCC patients with adjacent tumor-free oral mucosa, for all cases, we found a higher expression level in tumor cells than in the healthy keratinocytes." (PMID 28002801, 2017).
tumor (continued). "Taken together, this study has shown that the expression of both SEC62 and SOX2 shows differences between the primary tumor and lymph node metastases of HNSCC patients and between the lymph node metastases of HNSCC and CUP patients." (PMID 28002801, 2017). "All tissue slides showed SEC62 overexpression in tumor cells and no SEC62 expression in other cells." (PMID 36685175, 2022). "Overexpression of Sec62 promoted tumour growth in the mouse xenografts while Sec62 DA mutant failed to do so." (PMID 33858476, 2021). "After 2 years of follow-up, the levels of Sec62 were much higher in tumour tissues with early recurrence (20/60) than in non-recurrent tumours (40/60)." (PMID 31822656, 2019). "To determine whether different expression levels of SEC62 and SOX2 affect tumor cell biology, as indicated by our immunohistochemical analyses, we performed functional analyses using UM-SCC1 cells as an in vitro model." (PMID 28002801, 2017). "Additionally, only SEC62 positive patients showed p16 positive tumor cells in 20.4% of cases, while no SEC62 negative patient was p16 positive." (PMID 38201525, 2023). "To evaluate whether SEC62 and SOX2 expression exerts any influence on lymphatic metastasis of HNSCCs, we analyzed the expression levels of both genes in the primary tumor and the lymph node metastases from all 65 HNSCC patients using immunohistochemical staining." (PMID 28002801, 2017). "Finally, the fact that we used pretherapeutic tumor biopsies for immunohistochemical SEC62 staining might lead to a sampling bias as we could not take into account a potential intra-tumoral heterogeneity of SEC62 expression." (PMID 38201525, 2023). "In particular, no SEC62-specific inhibitors have been reported to date, but inhibition of Sec62 function by antagonizing cellular Ca2+ homeostasis by CaM antagonists has been proved to mimic SEC62 deletion in vitro by inhibiting migration and proliferation of human tumor cells." (PMID 37014697, 2023). "Additionally, p16 positive cases showed significantly higher SEC62 expression levels compared to p16 negative samples in our study cohort, which might have counteracted the well-known beneficial effects of HPV-associated tumor cell biology in terms of treatment response." (PMID 38201525, 2023).
infection (5 papers, 2009 to 2023). The state of being infected such as from the introduction of a foreign agent such as serum, vaccine, antigenic substance or organism. "Our data therefore indicate that Ube2g2 deficiency resulted in stabilisation of stress response chaperones along with increased expression of Sec62, which consequently triggers Sec62-dependent ER-phagy during infection." (PMID 37164963, 2023). "The overexpression of Sec62 promoted the phosphorylation of IRE1α at late infection times." (PMID 34532300, 2021).